MAP3K8 (mitogen-activated protein kinase kinase kinase 8)
Diseases named in the same sentence as MAP3K8 in open-access papers (continued):
Sharing a sentence is not in itself a finding about the gene and the disease.
autoimmune disease (5 papers, 2015 to 2025). A disorder resulting from loss of function or tissue destruction of an organ or multiple organs, arising from humoral or cellular immune responses of the individual to their own tissue constituents. "On the other hand, mTORC1 has been proposed to mediate TNF-induced IL-10 expression and the STAT3-initiated cascade in synovial macrophages, whereas pharmacological blockage of Cot/Tpl-2/MAP3K8 in macrophages has been suggested to induce therapeutic effects in various autoimmune disorders." (PMID 40806725, 2025). "Since our data provide a mechanistic link between hypoxia and immune cell function, and since these are important factors in infection, cancer, and autoimmune disease, MAP3K8 might be a promising therapeutic target for treatment of these diseases." (PMID 30463908, 2018). "This tissue damage and ROS production might subsequently lead to local hypoxia which further up-regulates MAP3K8 activity, contributing to the localized hypoxia observed in many autoimmune diseases." (PMID 30463908, 2018). "In many autoimmune diseases, a negative feedback loop between tissue damage and inflammation exists, where MAP3K8 promotes myeloperoxidase activity, ROS production, and recruitment of neutrophils and macrophages, causing tissue damage." (PMID 30463908, 2018).
bladder cancer (5 papers, 2018 to 2024). "Another MAPK, extracellular signal-regulated kinase (ERK), is involved in non-canonical type I IFN signaling in malignancy, where mitogen-activated protein kinase kinase kinase 8 (MAP3K8) and ERK phosphorylation were decreased upon IFNα treatment in bladder cancer cells." (PMID 33329603, 2020).
glioma (5 papers, 2020 to 2025). A benign or malignant brain and spinal cord tumor that arises from glial cells (astrocytes, oligodendrocytes, ependymal cells). "Causal links, particularly between MAP3K8, miRNA regulation, and glioma progression, require functional validation in cell-based and in vivo models." (PMID 40565357, 2025). "Especially, the role of MAP3K8 in glioma immune cells and its underlying molecular mechanisms are still unclear." (PMID 35004849, 2021). "We also performed the function and pathway enrichment analysis of MAP3K8 in glioma to explore its biological functions and underlying molecular mechanisms in glioma." (PMID 35004849, 2021). "Elevated expression of MAP3K8 was also found in high-grade glioma and was significantly associated with the WHO grade." (PMID 35004849, 2021). "ROC curve analysis of MAP3K8 demonstrated that the area under the ROC curve (AUC) was 0.710, which indicated high diagnostic value of MAP3K8 expression in glioma." (PMID 35004849, 2021). "We also performed function and pathway enrichment analysis to explore the biological function and underlying molecular mechanisms of MAP3K8 in glioma." (PMID 35004849, 2021). "The protein level of MAP3K8 in glioma tissues was significantly associated with the WHO grade." (PMID 35004849, 2021). "High expressions of MAP3K8 in renal clear cell carcinoma and glioma have been reported to correlated with poor survival." (PMID 40831931, 2025). "In clinical pathology specimens, the protein level of MAP3K8 was elevated in glioma tissues, in contrast to para-tumor tissues." (PMID 35004849, 2021). "GO enrichment, KEGG pathway analysis, and GSEA were performed to explore the biological functions of MAP3K8 in glioma." (PMID 35004849, 2021). "MAP3K8 is an independent prognostic indicator and significantly correlates with the progression of glioma." (PMID 35004849, 2021). "The expression MAP3K8 was also significantly associated with the PFI and DSS of glioma patients in TCGA dataset." (PMID 35004849, 2021). "The IHC results showed that the protein level of MAP3K8 was elevated in glioma tissues compared to para-tumor tissues." (PMID 35004849, 2021). "Our results revealed that MAP3K8 was an independent prognostic indicator and significantly correlated with the disease progression and poor clinicopathological features of glioma." (PMID 35004849, 2021). "More works are needed to explore the role of MAP3K8 in tumor-infiltrating neutrophil-mediated tumor immune response in glioma." (PMID 35004849, 2021). "Multivariate Cox regression analysis demonstrated that WHO grade and age were correlated with the OS of glioma patients.The results strongly indicated that MAP3K8 was an independent prognostic factor and correlated with the disease progression of glioma." (PMID 35004849, 2021). "MAP3K8 is an independent prognostic indicator and significantly correlates with the disease progression of glioma." (PMID 35004849, 2021). "For further validation, we investigated the expression of MAP3K8 in clinical pathology specimens by IHC in 94 glioma tissues and 27 para-tumor tissues." (PMID 35004849, 2021). "In total glioma, the expression of MAP3K8 was positively correlated with the enrichment of macrophages, eosinophils, neutrophils, and Th2 cells." (PMID 35004849, 2021). "Collectively, our study is the first to provide evidence that MAP3K8 was aberrantly overexpressed in glioma and correlated with poor clinicopathological features." (PMID 35004849, 2021). "Single-cell RNA sequencing data and immunohistochemistry analysis demonstrated that MAP3K8 is expressed in malignant and immune cells and mainly enriched in the microglia/macrophage cells of glioma." (PMID 35004849, 2021). "The gene expression profiles across all tumor samples and paired normal tissues demonstrated that MAP3K8 was overexpressed in glioma, including GBM and LGG." (PMID 35004849, 2021).
glioma (continued). "Single-cell RNA sequencing (RNA-seq) data and immunohistochemistry (IHC) analysis showed that MAP3K8 was expressed in malignant and immune cells and mainly enriched in the microglia/macrophage cells of glioma." (PMID 35004849, 2021). "Here, we found that MAP3K8 was aberrantly overexpressed in glioma and correlated with poor clinicopathological features." (PMID 35004849, 2021). "Analysis of OS in the CGGA and TCGA datasets showed that MAP3K8 was negatively correlated with the prognosis of glioma." (PMID 35004849, 2021). "Here, we discovered that MAP3K8 was aberrantly overexpressed in glioma and correlated with poor clinicopathological features of glioma by analysis on different datasets and immunohistochemistry staining." (PMID 35004849, 2021). "Importantly, MAP3K8 inhibitors have shown promise in preclinical models of inflammatory diseases and hematologic malignancies, but their application in gliomas remains untested." (PMID 40565357, 2025). "To date, the expression, clinical significance, biological role, and underlying molecular mechanisms of MAP3K8 in glioma have not been investigated yet." (PMID 35004849, 2021). "We firstly analyzed the relationship between MAP3K8 expression and immune infiltration in glioma." (PMID 35004849, 2021). "The expression, clinical significance, biological role, and the underlying molecular mechanisms of MAP3K8 in glioma have not been investigated yet." (PMID 35004849, 2021). "In addition, we found that the expression of MAP3K8 was obviously elevated in high-grade glioma, especially in GBM." (PMID 35004849, 2021). "In glioma, MAP3K8 might act as an essential modulator of polarization and function for tumor-associated macrophages." (PMID 35004849, 2021). "Elevated expression of MAP3K8 was also found in high-grade glioma." (PMID 35004849, 2021). "In view of the comprehensive regulatory role of MAP3K8 in tumor immunity, therapeutic regimen blocking MAP3K8 might be a promising strategy for the development of more integrative and specific cancer immunotherapy for glioma." (PMID 35004849, 2021). "Nevertheless, the expression, clinical significance, and the biological role of MAP3K8 in glioma have yet to be investigated and remain unclear." (PMID 35004849, 2021). "The function and pathway enrichment analyses of MAP3K8 in glioma indicated that MAP3K8 might participate in the tumor immune microenvironment and immune regulation." (PMID 35004849, 2021). "Our results indicated that MAP3K8 might play an essential role in tumor immunoregulation and work as a putative drug target in glioma." (PMID 35004849, 2021). "Our results indicated that the role of MAP3K8 in macrophages might be a promising research direction in glioma." (PMID 35004849, 2021). "Correlation analysis of MAP3K8 with immune infiltration in glioma was performed." (PMID 35004849, 2021). "The role of MAP3K8 in regulating neutrophil activation, leukocyte migration, leukocyte cell–cell adhesion, and B-cell-mediated immunity for glioma immunoregulation remains unclear." (PMID 35004849, 2021). "In a nutshell, MAP3K8 is a prognostic biomarker and is correlated with immune response in glioma." (PMID 35004849, 2021). "Univariate Cox regression analysis demonstrated that MAP3K8 expression, WHO grade, 1p/19q codeletion, and age were correlated with the OS of glioma patients." (PMID 35004849, 2021). "The expression of MAP3K8 was positively correlated with immune infiltration, including effector memory CD4+ T cells, plasmacytoid dendritic cells, neutrophils, myeloid dendritic cells, mast cells, and macrophage in glioma." (PMID 35004849, 2021). "MAP3K8 might play an essential role in tumor immunity, and inhibition of MPA3K8 is a plausible strategy for glioma immunotherapy." (PMID 35004849, 2021). "In addition, Western blot showed that the protein level of MAP3K8 was enhanced in glioma cell lines compared with that in normal human astrocyte and glial cells." (PMID 35004849, 2021).
glioma (continued). "The expression of MAP3K8 was positively correlated with the enrichment of memory CD4+ T cells, effector memory CD4+ T cells, plasmacytoid dendritic cells, neutrophils, myeloid dendritic cells, mast cells, macrophages, M2 macrophage, and M1 macrophage in glioma." (PMID 35004849, 2021). "In view of the correlation analysis of MAP3K8 with immune infiltration, the expressions of immune checkpoint molecules, chemokines, and chemokine receptors in glioma, MAP3K8 might play an essential role in tumor immunity, and the inhibition of MPA3K8 is a plausible strategy for glioma immunotherapy." (PMID 35004849, 2021).
Insulin resistance (5 papers, 2012 to 2022). Increased resistance towards insulin, that is, diminished effectiveness of insulin in reducing blood glucose levels. "Altogether, the findings argue against MAP3K8 to be a central kinase in regulating pro-inflammatory signals leading to insulin resistance." (PMID 24586913, 2014). "However, MAP3K8 deficient mice were not protected against HFD-induced adipose tissue macrophage infiltration or the development of insulin resistance." (PMID 24586913, 2014). "Together, the data in both human and mouse show that MAP3K8 is involved in local adipose tissue inflammation, specifically for IL-1β and its responsive cytokines IL-6 and IL-8, but does not seem to have systemic effects on insulin resistance." (PMID 24586913, 2014).
liver fibrosis (5 papers, 2014 to 2024). "As expected, Map3k8–deficient Kupffer cells had reduced TLR-induced IL-1β and pro-fibrotic gene expression, which the authors suggested was responsible for the reduced hepatic fibrosis in vivo." (PMID 27487182, 2016).
lymphoma (5 papers, 2012 to 2023). A malignant (clonal) proliferation of B- lymphocytes or T- lymphocytes which involves the lymph nodes, bone marrow and/or extranodal sites. "Another MAP3K, Cot/MAP3K8, may be the primary activator of MEK in this lymphoma." (PMID 22852078, 2012).
ovarian carcinoma (5 papers, 2015 to 2022). A malignant neoplasm originating from the surface ovarian epithelium. "Taken together, our data show that MAP3K8 regulates key features of ovarian cancer cells and promotes tumourigenesis in vivo, which explains, at least in part, that the high level of MAP3K8 protein is associated with a poor prognosis in human HGSC." (PMID 26456302, 2015). "In ovarian carcinomas, MAP3K8 promoted cell proliferation and migration by regulating the cell cycle and adhesion dynamics." (PMID 35004849, 2021). "By combining analyses on HGSC patient cohorts, ovarian cancer cells and patient-derived xenografts, we demonstrate that MAP3K8 controls cancer cell proliferation and migration by regulating key players in G1/S transition and adhesion dynamics." (PMID 26456302, 2015). "First, we observed that inactivating either of the two protein kinases was sufficient to reduce cyclin D1 protein levels in ovarian cancer cells, confirming that both MAP3K8 and p90RSK were required for cyclin D1 expression." (PMID 26456302, 2015). "Prior to any immunohistochemistry (IHC) analysis on human HGSC samples, we confirmed the specificity of our antibody for MAP3K8 protein by performing IHC on MAP3K8-depleted SKOV3 ovarian cancer cells in the same conditions as for the clinical samples." (PMID 26456302, 2015). "Using shRNA targeting MAP3K8 or MAP3K8 kinase inhibitor, we have demonstrated for the first time that MAP3K8 positively controls ovarian cancer cell proliferation, migration and invasion, as well as tumour growth in mouse models." (PMID 26456302, 2015). "Upon KI treatment, MAP3K8 inhibition significantly reduced both cell migration and cell invasion, in the two human ovarian cancer cell lines tested." (PMID 26456302, 2015). "As we observed that MEK signalling is the main pathway activated downstream of MAP3K8 in ovarian cancer cells, we investigated the role of the MAP3K8/MEK/ERK pathway in HGSC patients." (PMID 26456302, 2015). "MAP3K8 inhibition by KI significantly reduced the total number of cells in the two ovarian cancer cell lines tested." (PMID 26456302, 2015). "In this study, the authors identify MAP3K8 as a potential predictive marker for MEK inhibitor treatment in patients with aggressive ovarian cancer." (PMID 26456302, 2015). "Moreover, MAP3K8 is a key player in ovarian tumourigenesis by controlling progression through the cell cycle and the invasive properties of ovarian cancer cells." (PMID 26456302, 2015). "This further argues that the cell-autonomous function of MAP3K8 in ovarian cancers could be dominant over the anti-tumour effect mediated by CD8+ cytotoxic-T lymphocytes or by tumour necrosis factor-α-producing M1 macrophages." (PMID 26456302, 2015). "Thus, MEK was the only common pathway downregulated upon MAP3K8 inhibition using either of the two complementary strategies in the two independent ovarian cancer cell lines tested." (PMID 26456302, 2015). "Thus, our data indicate that MAP3K8 inhibition significantly reduces ovarian cancer cell proliferation, migration and invasion in vitro, as well as tumour growth in vivo." (PMID 26456302, 2015). "This hypothesis is supported by our data revealing that MAP3K8 protein levels correlate with activation of MEK pathway in ovarian cancer cells, mouse tumour models and human HGSC." (PMID 26456302, 2015). "Thus, by combining analyses of HGSC patients, ovarian cancer cells and mouse xenograft models, we have unambiguously demonstrated that MAP3K8 fulfills a pro-tumourigenic role in ovarian cancers." (PMID 26456302, 2015). "Finally, to fully demonstrate p90RSK was the key effector mediating MAP3K8/MEK actions in ovarian cancer cells, we inactivated it alone or in combination with MAP3K8 silencing." (PMID 26456302, 2015). "Moreover, we found that p90RSK, a main effector of MEK/ERK signalling, could mediate MAP3K8 cell-autonomous functions in ovarian cancer." (PMID 26456302, 2015).
ovarian carcinoma (continued). "Therefore, MAP3K8 functions are most reliably mediated through MEK in ovarian cancer cells." (PMID 26456302, 2015). "Interestingly, MAP3K8 phosphorylation state also correlated with MEK activation, further highlighting that MAP3K8 kinase could be a significant readout for MEK activation in ovarian cancers." (PMID 26456302, 2015). "Finally, using mouse xenograft models, we observed that tumour growth was severely impaired following MAP3K8 depletion compared with control tumours, result validated in shMAP3K8_1 and -2 stable cell lines derived from the two independent ovarian cancer cell lines tested." (PMID 26456302, 2015). "Kras/Braf mutations in low-grade serous ovarian carcinomas (LGSOC) and MAP3K8 accumulation in high-grade serous ovarian carcinomas (HGSOC) induce constitutive MEK/ERK activation and significantly sensitize ovarian cancer cells to MEKi." (PMID 29458390, 2018). "As observed upon KI treatment, we confirmed that MAP3K8 stable silencing significantly reduced cell proliferation in all ovarian cancer cell lines tested, without affecting their viability." (PMID 26456302, 2015). "We used a second strategy to confirm the role of MAP3K8 in ovarian cancer cells and tumour development—KI could not be tested in vivo due to expensive cost established by the manufacturer." (PMID 26456302, 2015). "It would thus be interesting to test whether MAP3K8 could be a general prognostic marker in ovarian cancers irrespective of the grade." (PMID 26456302, 2015). "Indeed, we observed a clear correlation between the MAP3K8 protein level and its phosphorylation state at the T290 and S400 phosphorylation sites, indicating that the protein level and kinase activity of MAP3K8 are correlated in SKOV3 ovarian cancer cells." (PMID 26456302, 2015).
clear cell renal cell carcinoma (4 papers, 2020 to 2025). "In this study, we used bioinformatics tools to explore expression level, prognostic values, and interactive networks of MAP3K8 in renal clear cell carcinoma (ccRCC)." (PMID 34567061, 2021). "In clear cell renal cell carcinoma (CCRC), the overexpression of MAP3K8 correlates with poor survival and may be involved in in cancer-related inflammation through NF-κB and Toll-like receptor signaling pathways." (PMID 39944684, 2025).
psoriasis (4 papers, 2020 to 2024). An autoimmune condition characterized by red, well-delineated plaques with silvery scales that are usually on the extensor surfaces and scalp. "The inhibition of MAP3K8 has shown therapeutic potential in various inflammatory diseases, including IBD, RA, and psoriasis, highlighting its value as an important therapeutic target." (PMID 39595128, 2024). "The childhood genes were MIR-1914, MIR-647 and MAP3K8 (common wart) and TNF (psoriasis)." (PMID 37697338, 2023).
Candida infection (3 papers, 2017 to 2023). "In this study we also demonstrate that MAP3K8 plays an important role in Candida infection by modulating cytokine production." (PMID 28727728, 2017). "Overall, these experiments demonstrate that MAP3K8 regulates cytokine levels upon Candida infection." (PMID 28727728, 2017). "The link of MAP3K8 with TLR-signalling suggests that the innate immune response is important in the context of Candida infection." (PMID 28727728, 2017). "We should note that IFNγ, one of the most crucial cytokines for efficient host defence for systemic candidiasis, decreased compared to DMSO after stimulation with Candida conidia (P = 0.057) for 48 hours at 200 μM of MAP3K8 inhibitor." (PMID 28727728, 2017).
COVID-19 (3 papers, 2020 to 2023). A disease caused by infection with severe acute respiratory syndrome coronavirus 2. "Two new targets identified using our approach, including PTEN and MAP3K8, were potentially key targets for the treatment of COVID-19." (PMID 37037848, 2023). "We followed by MD simulations of MAP3K8 and licoisoflavone B with the highest binding energy, which demonstrated that licorice may be considered an effective candidate for the treatment of COVID-19 through MAP3K8 [MD simulations analysis]." (PMID 37037848, 2023). "Therefore, licorice has been proposed as an effective candidate for the treatment of COVID-19 through PTEN, MAP3K8, Mpro, S-protein and ACE2." (PMID 37037848, 2023).